DAPK1 (death associated protein kinase 1)
Diseases named in the same sentence as DAPK1 in open-access papers (continued):
Sharing a sentence is not in itself a finding about the gene and the disease.
tumor (continued). "Silencing of DAPK1 via hypermethylation of its promoter has been suggested to influence tumour progression and metastasis in cancers such as CLL and DLBCL and is a marker of poor survival." (PMID 32306542, 2020). "Death-Associated Protein Kinase-1 (DAPK1), which controls several functions of the human cell, is well-known for its role in apoptosis, autophagy, and suppressing tumour growth." (PMID 31809612, 2020). "DAPK1 mRNA expression was significantly decreased in the metastatic ccRCC tissues compared to the primary ccRCC tumor tissues in the GSE43477 ccRCC dataset." (PMID 33201837, 2020). "Previous studies also show that DAPK1 is a tumor suppressor gene that inhibits tumor growth and metastasis by promoting apoptosis and autophagy." (PMID 33201837, 2020). "Low DAPK1 expression correlates with the upregulation of genes involved in metastasis, drug resistance, tumor invasiveness, and the ER phagosome pathway." (PMID 33201837, 2020). "The application of DAPK1-mediated necroptosis suppression is likely tumor-type and tumor stage dependent." (PMID 32366830, 2020). "DAPK1 as a tumour suppressor regulates autophagy and apoptosis (mediator of gamma-interferon induced programmed cell death) thereby acting as an important player in the pathway involved in the ER stress-induced apoptosis." (PMID 32566040, 2020). "Apart from its role in apoptosis, DAPK1 participates in a wide variety of cellular events including autophagy, membrane blebbing, and stress fiber formation that all contribute to its tumor-suppressing functions." (PMID 32366830, 2020). "Immunohistochemical analysis of xenograft tumor sections showed significantly higher levels of apoptosis in the xenograft tumors derived from DAPK1 overexpressing 786O-R cells compared to the corresponding controls." (PMID 33201837, 2020). "Our study demonstrates that DAPK1 is an independent prognostic factor in ccRCC patients and its expression correlates with tumor stages and grades." (PMID 33201837, 2020). "On the other hand, DAPK1 acts as a tumor suppressor, through the inhibition of TACSDT2, a receptor that transduces Ca2+ signals and subsequently, leads to enhanced proliferation, invasion, and self-renewal signals." (PMID 33238574, 2020). "Functionally, CUX1 upregulated expression of caspases and death associated protein kinase 1 (DAPK1), known as mediators of tumour progression and resistance to cytotoxic drugs." (PMID 32707646, 2020). "DAPK1 mRNA levels were significantly lower in tumor tissues than normal kidney tissues in TCGA-KIRC dataset (n=428)." (PMID 33201837, 2020). "We suggest a novel and even more comprehensive picture of DAPK1 ́s antimetastatic functions by giving the first time experimental data that it diminishes an effective tumor cell–ECM interaction." (PMID 31772156, 2019). "For in vitro analysis of invasive potential of HCT116 and DAPK1 ko clones 7/6, 10/8 and 21/9 tumor cells, 3D-tumor spheroids were embedded in matrigel and cell penetration from the spheroid core into the environment was monitored over time." (PMID 31772156, 2019). "To closer investigate which tumor–stroma processes were up- and down-regulated upon DAPK1 ko we performed pre-ranked gene-set enrichment analysis (pre-ranked GSEA) using all gene sets in the BROAD Database (MsigDB) gene-set collection v6.2." (PMID 31772156, 2019). "In summary, we have successfully modeled the in vivo situation that DAPK1 is mostly lost at the tumor invasion front of CRC." (PMID 31772156, 2019). "Tumor differentiation was correlated with the DAPK1 SNVs rs11141901 (p-value = 0.041) and rs1041326 (p-value = 0.005)." (PMID 31528229, 2019). "This establishes a functional link between tumor progression and the DAPK1 regulation mechanism, but the link to neuronal cell death has not been determined." (PMID 31248062, 2019). "DAPK1 exerts its tumor suppressor function at least partly via suppressing the metastasis associated TACSDT2." (PMID 31772156, 2019).
tumor (continued). "In the chorioallantoic membrane (CAM) model, we showed an increased tumor budding and metastatic potential when DAPK1 was lost in tumor cells supporting its role as a tumor suppressor." (PMID 31772156, 2019). "Typically, dapk-1 has been studied in the context of its suppression in tumor growth and metastasis but additional roles emerged in last years." (PMID 31001128, 2019). "In confocal immunofluorescence images we showed that pERK1/2 in HCT116 cells is predominantly localized in the cytoplasm, whereas in the three DAPK1 ko clones pERK1/2 expression was remarkably increased in the nuclei of tumor cells in vitro." (PMID 31772156, 2019). "Since DAPK1 is lost in this aggressive cell subpopulation at the tumor invasion front we suggest a tumor suppressor role for DAPK1." (PMID 31772156, 2019). "Next we confirmed the highly invasive behavior of DAPK1 ko tumor cells in another 3D ex vivo model, where tumor cells were applied and cultured on precision-cut tissue slices of rat brain." (PMID 31772156, 2019). "To mirror-image DAPK1 loss in tumor buds and to shed more light into the role of DAPK1 in CRC aggressiveness we designed unique CRISPR/Cas9 DAPK1 knockout (ko) cell lines and characterized the knockout phenotype in vitro and in vivo." (PMID 31772156, 2019). "It should be mentioned that DAPK1 also plays an important role in regulating cell apoptosis and tumor suppression; therefore, a reasonable manipulation of DAPK1 activity should be considered to overcome the potential side effects of DAPK1 inhibition." (PMID 31892243, 2019). "DAPK1 acts as a tumor suppressor to play a rate‐limiting effector in an endoplasmic reticulum (ER) stress‐dependent apoptotic pathway." (PMID 29665256, 2018). "The mean difference of vimentin and DAPK1 serum levels between tumour area groups was statistically insignificant (p = 0.072)." (PMID 28616237, 2017). "DAPK1 serum levels weakly correlated with cancer duration (r = 0.098, p = 0.27) and tumour size (r = 0.40, p < 0.05)." (PMID 28616237, 2017). "Hypermethylation of host cell tumor suppressor genes including E-cadherin (CDH1), Cell Adhesion Molecule 1 (CADM1) and Death-Associated Protein Kinase 1 (DAPK1) was reported in recent studies." (PMID 28881717, 2017). "The dissimilar results for the different sources for the control group suggested that the degree of DAPK1 methylation in the normal tissue adjacent to tumor tissue was higher than that in normal tissues." (PMID 28934284, 2017). "The results suggest that DAPK1 is down-regulated in tumor/cirrhotic liver specimens compared to non-tumor and healthy liver specimens." (PMID 28740751, 2017). "With DAPK1, patient’s age weakly but positively correlated with the concentration of DAPK1 (r = 0.393, p < 0.05) just as tumour stage which also weakly correlated with DAPK1 serum levels (r = 0.098, p = 0.27) and tumour area." (PMID 28616237, 2017). "DAPK1 functions as a tumor suppressor and regulates apoptosis (mediator of gamma-interferon induced programmed cell death) and autophagy which act as a critical element of the pathway involved in the ER stress-induced apoptosis." (PMID 28616237, 2017). "Methylation of DAPK1 in tumor biopsies has proven to be an independent prognostic marker in DLBCL and is also methylated in a large proportion of the patients." (PMID 27610206, 2016). "On the other hand, DAPK1 is a tumor suppressor gene, known to suppress tumor growth and metastasis by promoting autophagy and apoptosis." (PMID 27445685, 2016). "Death-associated protein kinase 1 (DAPK1) and its related calcium-regulated serine/threonine kinases play a wide variety of roles in cell death and tumor suppression." (PMID 27661253, 2016).
tumor (continued). "A subgroup analysis according to the tumor location revealed that the frequency of DAPK-1 promoter methylation was significantly related to the intestinal cancerous tissue when the tumor was detected in the upper third of the stomach (p = 0.02)." (PMID 26810771, 2016). "In primary cancers, aberrant DNA methylation has been observed at tumor-suppressor genes, including DAPK1, DLC1, p15, p16, and RASSF1A." (PMID 26823082, 2016). "In only 38 % (6/16) of the tumor-adjacent and tumor-distant tissues, the DAPK1 promoter was found to be methylated, compared to 63 % (10/16) in tumors." (PMID 26370119, 2015). "The DAPK1 protein is known to be involved in the suppression of cancer formation and metastasis via apoptosis and, thus, is considered to be a tumor suppressor gene." (PMID 25435999, 2015). "This approach would inactivate the DAXX pathway for tumor promotion, and consequently restore the activity of the DAPK1 and DAPK3 tumor suppressors." (PMID 26097870, 2015). "Several studies have shown that DAPK1 is a tumor-suppressor gene and down-regulated in many types of cancers." (PMID 26626260, 2015). "Because of the moderate heterogeneity between studies, a sensitivity analysis and subgroup analyses by histological tumor types, sources of control samples and assays used to evaluate DAPK1 promoter methylation were performed." (PMID 26267895, 2015). "The correlations between DAXX and DAPK1/3 expression will be based on the tumor grade, stage, and disease metastasis." (PMID 26097870, 2015). "In many types of cancer, including PCa, tumor suppressors, such as DAPK1 and DAPK3, are downregulated, a process that facilitates cancer metastasis." (PMID 26097870, 2015). "Because of its ability to sensitize cells to many of the apoptotic signals that are encountered during malignant transformation DAPK1 is considered to be a tumour suppressor gene." (PMID 25229255, 2014). "DAPK1 is a calcium/calmodulin-dependent serine/threonine protein kinase involved in apoptosis and tumor suppression." (PMID 25202403, 2014). "Concordant MSP results of miR-34b/c, miR-34a and DAPK1 between bone marrow cells and peripheral blood cells were demonstrated, and hence both peripheral blood and marrow tumor cells are valid for methylation study." (PMID 24559316, 2014). "Co-transfection of PDCD6 and DAPk1 cDNA into a tumour cell line accelerated apoptosis via the caspase-3 dependent pathway." (PMID 23880846, 2013). "Of note, DAPK-1 is commonly silenced in human cancers bymethylation and has tumor and metastasis suppressorproperties." (PMID 23307622, 2012). "DAPK1 was identified as a familial tumor suppressor gene and methylation is found in the DAPK1 promoter region in CLL." (PMID 22735547, 2012). "AURKC is known to be over expressed in several cancer cell lines while DAPK1 is a tumour suppressor candidate." (PMID 22087225, 2011). "Another autophagy inducing gene DAPK-1 is frequently silenced in human cancers by methylation and demonstrates tumor and metastasis suppressor properties." (PMID 20184741, 2010).
tumor (continued). "The methylation frequency of DAPK-1 was 80% (16 out of 20) in pTa, 80% (24 out of 30) in pT1 and 70% (14 out of 20) in muscle invasive ⩾pT2 tumour disease." (PMID 17133271, 2006). "The median NIM levels for DAPK-1 in G1/2 (G3) tumours were 3% (0%) in pT1, 1% (7%) in pT2, and 0% (13%) in ⩾pT3 tumours." (PMID 17133271, 2006). "The median NIM levels for APAF-1 were 42% in smaller tumours and 60% in larger ones; the corresponding levels for DAPK-1 were 2 and 3%, respectively." (PMID 17133271, 2006). "Notably, KI-AA1524/CIP2A also interacts with several phosphorylated PP2A substrates involved in tumor growth, including c-Myc, polo-like kinase 1 (Plk1), E2F1, Akt, and death-associated protein kinase 1 (DAPK1)." (PMID 41154660, 2025). "Furthermore, CYP1B1 hinders apoptosis by inhibiting the activation of caspase-1 (CASP1) and downregulating pro-apoptotic DAPK1, thereby providing tumor cells with a survival advantage." (PMID 41155673, 2025). "Moreover, s-DAPK-1 was found to interact with a variety of proteins involved in tumor progression and gene regulation, including a prion protein and histone H2B type 2-E (H2B2E)." (PMID 40699815, 2025). "Furthermore, DAPK1 phosphorylation activity contributes to cell necrosis, apoptosis, autophagy, and tumor biology." (PMID 40454931, 2025). "DAPK1 is well-known as a tumor suppressor gene due to its cell death inducer function." (PMID 40918124, 2025). "Since DAPK-1 promotes autophagy and apoptosis, it may, in turn, inhibit tumor development and metastasis." (PMID 39081443, 2024). "DAPK1 acts as a tumor suppressor and controls tumor growth in the early stages." (PMID 39057063, 2024). "Firstly, the underlying mechanism of the identified ARGs, especially AKT2 and DAPK1, in tumor immune microenvironment and OV progression remained largely unknown, which needs further investigation." (PMID 38310291, 2024). "Additionally, DAPK1 can impact tumor growth and metastasis through mechanisms such as regulating apoptosis, suppressing cell migration, and inhibiting tumor angiogenesis." (PMID 38463514, 2024). "DAPK1 is a protein kinase that regulates tumor suppression, autophagy, and apoptosis." (PMID 37446908, 2023). "DAPK1 belongs to a family of serine/threonine protein kinases and functions as a tumor suppressor." (PMID 36830707, 2023). "DAPK-1 also supports autophagy and apoptosis, thereby suppressing tumour growth and metastasis." (PMID 37372454, 2023). "Due to its potential as a therapeutic target, a deeper understanding of the role of DAPK-1 in cell death and tumour suppression may result in the development of more effective and specific therapeutic interventions." (PMID 37372454, 2023). "As a result of these findings, the tumour suppressor, DAPK-1, might eventually lead to more effective cancer therapeutic strategies by suppressing Pin1 oncogenic activity." (PMID 37372454, 2023). "MORC2 was found to function in KIRC by downregulating tumor suppressor DAPK1 via DNA methylation." (PMID 37737260, 2023). "WNT5A, like DAPK1, is a tumor suppressor which can also modulate T cell activation." (PMID 38129593, 2023). "DAPK-1 is a tumor suppressor induced by IFN-γ and can also influence the expression of IFN-γ." (PMID 38129593, 2023). "DAPK-1 is a tumour-suppressor gene that is hypermethylated in most human cancers." (PMID 37372454, 2023). "The IL-8 OE + DAPK1 OE group displayed the largest tumor size." (PMID 36932390, 2023). "This study suggests that DAPK1 can be used as a target for tumor targeted therapy." (PMID 37576398, 2023). "We used proteomic analysis to identify proteins that are dysregulated in DAPK1 ko tumor cells." (PMID 35625969, 2022). "Comparing to normal group, ATG2B, ATG10, DAPK1 were all high expressed in tumor and cell lines." (PMID 35902797, 2022).
tumor (continued). "DAPK1 has also been found to affect apoptosis and autophagy in various tumor cells." (PMID 35082934, 2022). "Therefore, DDX20, the downstream gene of DAPK1, appears to be both an oncogene and an oncogene suppressor in different tumor types." (PMID 36290392, 2022). "DAPK1 isoform plays an essential role as a tumor suppressor and inhibitor of metastasis." (PMID 36145271, 2022). "In vivo tumorigenesis confirmed that DAPK1 knockout significantly promoted tumor cell growth." (PMID 35935258, 2022). "Therefore, HCT116 DAPK1 ko cells were transfected with uPAR siRNA and scrRNA, respectively, during the generation of 3D-tumor spheroids and subsequently embedded in Matrigel to simulate the invasion into the ECM." (PMID 35625969, 2022). "Our results on DAPK1 indicate how enhanced tumor budding potential and active ECM remodeling might be coupled, thus facilitating this invasive process." (PMID 35625969, 2022). "In conclusion, suppression of DAPK1 may accelerate tumor growth and result in the upregulation of C3, TIMP-1, and AHSG expression and downregulation of KNG1 expression." (PMID 35935258, 2022). "DAPK1 is a serine/threonine kinase, a tumor suppressor protein that promotes apoptosis, while PPP2R2A, a regulatory subunit of protein phosphatase 2A (PP2A), controls the pathway of AKT signaling associated with tumor growth." (PMID 34305611, 2021). "When we divided the dataset into two groups according to DAPK1 expression levels, we observed a larger tumor size and higher stemness index (SI) in the low DAPK1 group than in the high DAPK1 group, indicating a higher proliferation rate and more stem cell-like features of these tumors, respectively." (PMID 34831219, 2021). "Likewise, there was an increased expression of the death-associated protein kinase 1 (DAPK1) and decreased expression of serine/threonine-protein phosphatase 2A (PPP2R2A) in tumor tissues." (PMID 34305611, 2021). "DAPK1 could function either as a tumour suppressor or as an oncogenic molecule in different cellular context." (PMID 33509203, 2021). "Down-regulated DAPK1 has a relationship to tumor recurrence as well as metastasis." (PMID 34976784, 2021). "However, special consideration is needed to overcome the potential side effects of DAPK1 inhibition by modulating DAPK1 activity because DAPK1 also plays a part in regulating cell growth and tumor suppression." (PMID 34239362, 2021). "Whether downregulation of DAPK1 in several tumor types may provide an opportunity to target these cancers with necroptosis-inducing agents warrants further exploration." (PMID 32366830, 2020). "Thus, chemoradiation has the capacity to increase DAPK1 mRNA levels and reduce the number of tumor cells." (PMID 32328088, 2020). "DAPK1 is a tumor suppressor and is specifically downregulated in many types of cancer." (PMID 32366830, 2020). "In addition, advanced tumour stage and clinically aggressive phenotypes were reported in various cancer types, where DAPK1 was lost." (PMID 32707646, 2020). "Thus, in tumor cell lines, it has been described that antioxidants increase the expression of DAPK1, and that ROS facilitate protein phosphatase 2A (PP2A)-mediated dephosphorylation of pDAPK1 to render the active, non-phosphorylated, DAPK1 form." (PMID 33265962, 2020). "Interestingly, DAPK1 was found to be involved in the cross talk of tumor cells with macrophages of the stroma environment." (PMID 31772156, 2019). "Tracking green fluorochrome-labeled tumor cells, we found larger areas of invasion for DAPK1 ko clones one day after transplantation reflecting their increased invasive capability in a physiological 3D matrix in contrast to HCT116 wildtype cells (*P < 0.05; **P < 0.01)." (PMID 31772156, 2019).